INS (insulin)
Diseases named in the same sentence as INS in open-access papers (continued):
Sharing a sentence is not in itself a finding about the gene and the disease.
Hypoglycemia (continued). "In type 1 diabetic patients, hyperglycemia is primarily related to the loss of endogenous insulin secretion, while the impaired glucagon response to hypoglycemia explains the susceptibility to abnormally low glucose values." (PMID 29725320, 2018). "Compared to continuous subcutaneous insulin infusion, these systems are improving glucose control and reducing the risk of hypoglycemia significantly." (PMID 29422651, 2018). "In patients with a history of DM, common causes of hypoglycemia are exogenous drugs such as sulfonylureas and insulin, and decreased glucose delivery such as with fasting." (PMID 29849273, 2018). "Where glycemic targets have been achieved with metformin monotherapy, the use of metformin during pregnancy has been associated with a lower risk of neonatal hypoglycemia and less maternal weight gain than insulin." (PMID 29508275, 2018). "Assessments of GH secretion using stimulation tests of insulin- and clonidine-induced hypoglycemia showed deficiencies in secretion." (PMID 30542321, 2018). "Despite insulin availability, there are adverse effects of exogenous insulin, such as hypoglycemia, weight gain, and the risk of cancer." (PMID 30347680, 2018). "Hypoglycemia associated with intensive exercise is also reported in diabetic patients receiving insulin." (PMID 29590261, 2018). "Although increasing the basal insulin dose and/or adding mealtime insulin is often effective, this approach can increase the risk of hypoglycemia and lead to weight gain in an often overweight population." (PMID 29688502, 2018). "Insulinoma is a type of functional pancreatic neuroendocrine tumor (pNET) that originates from islet beta cells, which excessively secrete insulin and cause hypoglycemia." (PMID 30522468, 2018). "When insulin/GLP-1RA fixed-ratio combinations are compared with basal insulin, a superiority in reducing HbA1c is observed, with overall benefit also in weight neutrality or weight loss, reduced hypoglycemia risk, and reduced insulin-dose requirement." (PMID 29636825, 2018). "Another relevant observation from this study is that late post-exercise hypoglycemia risk was similar to rest interventions with the implementation of an 80% basal insulin reduction for moderate exercise and with pump suspension for the intense exercise." (PMID 30713524, 2018). "SGLT2 inhibitors, when used alone or in combination with metformin, are also associated with reduced risk of hypoglycemia by increasing plasma glucagon concentrations and decreasing plasma insulin concentrations." (PMID 29535389, 2018). "Basal-bolus insulin therapy is a more intensive treatment program that can be associated with greater hypoglycemia risk." (PMID 29255628, 2018). "Recently, two clinical trials showed that, among patients with T1DM and in T2DM treated with insulin (and with at least one hypoglycemia risk factor), the Deg treatment resulted in a reduced rate of overall symptomatic hypoglycemia, as compared to Glar-100." (PMID 29619381, 2018). "On the other hand, glibenclamide, a potent sulfonylurea used orally in small doses in the management of type 2 DM, causes stimulation of pancreatic beta cells leading to the release of insulin and causes hypoglycemia." (PMID 30323764, 2018). "As insulin was injected as a bolus in the patient's vein to cause hypoglycemia for CPST, this gave us an opportunity to study the underlying link between the iatrogenic hypoglycemia and cardiac arrhythmia." (PMID 30105256, 2018). "In contrast, the combination of DPP4i with basal insulin has been reported to typically produce a more robust postprandial glucose-lowering effect and lower risk of hypoglycemia than the combination with other types of insulin." (PMID 30349614, 2018). "IAS cannot easily be distinguished on clinical grounds from tumoral or other forms of hyperinsulinemic hypoglycemia, which includes hypoglycemia caused by surreptitious insulin administration." (PMID 30085133, 2018).
Hypoglycemia (continued). "The target of FBG intype 2 diabetics should improve compliance, reduced costs associated hypoglycemia, use of expensive prandial insulin and costassociated with frequent glucose monitoring at home." (PMID 31404422, 2018). "GLP-1RAs improve glucose homeostasis mainly through their most well-characterised effect, augmentation of glucose-stimulated insulin secretion, but also due to increase in insulin sensitivity and in the risk of hypoglycaemia." (PMID 30545359, 2018). "The insulin dose causing hypoglycemia was increased from 40 nmol/kg insulin alone to 160 nmol/kg insulin in the fixed ratio." (PMID 29558502, 2018). "When insulin therapy is required in patients with hepatic impairment, the choice should be regimens with low risk of hypoglycemia." (PMID 29508275, 2018). "DPP4i drugs also have a minimal risk of hypoglycemia due to their glucose-dependent mechanism of action regarding the regulation of insulin and glucagon secretion." (PMID 29511288, 2018). "IGF-I stimulates a reduction in blood glucose and circulating insulin levels and therefore, can cause hypoglycaemia." (PMID 29695048, 2018). "The risk of hypoglycemia increased in SGLT2i/DPP4i compared to that in PCB/DPP4i only when insulin or sulfonylureas were included as a background therapy." (PMID 29535389, 2018). "Rapid gastric emptying is also associated with postprandial hypoglycemia induced by excessive insulin release." (PMID 29767743, 2018). "Treatment with these agents is complicated by the fact that renal disease is an independent risk factor for hypoglycemia through several mechanisms including decreased renal insulin clearance and reduced renal glucose production during counterregulation." (PMID 30252913, 2018). "Patients with long QT syndrome due to rare loss-of-function mutations in the human ether-á-go-go-related gene (hERG) have prolonged QT interval, risk of arrhythmias, increased secretion of insulin and incretins and impaired glucagon response to hypoglycemia." (PMID 29548277, 2018). "Insulin, sulfonylureas, and meglitinides due to their glucose-independent mechanism of action cause a high risk of hypoglycemia." (PMID 29527102, 2018). "Insulin autoimmune syndrome (IAS, Hirata's disease) is a rare hypoglycemic disorder characterized by spontaneous hypoglycemia associated with extremely high circulating insulin levels and positive anti-insulin antibody results." (PMID 30462811, 2018). "In the current analysis, the risk of hypoglycemia increased with age and the use of basal-bolus insulin therapy." (PMID 29255628, 2018). "Insulin therapy is required to control BG levels in patients with T1D, but is associated with hypoglycemia, the major barrier to insulin titration and optimal glycemic control." (PMID 29549574, 2018). "In this study, we should pay more attention to prevent hypoglycemia attack in those high risk diabetic patients who were older, with chronic kidney disease and prescribed medications such as insulin, sulfonylurea, metformin and loop diuretics in Asia." (PMID 30355965, 2018). "Digestive system associated disease was the most common concurrent cause for hypoglycemia (n 17, 27.9%), followed by insulin administration error (n 8, 13.1%), acute kidney injury (n 7, 11.5%), skipped meal (n 7, 11.5%) and urinary tract infection (n 6, 9.8%)." (PMID 29685177, 2018). "Use of SUs and other insulin secretagogues with high risk of hypoglycemia should be used with caution." (PMID 29508275, 2018). "Basal insulin is a highly effective treatment in reducing fasting blood glucose, but it is associated with considerable risk of hypoglycemia and weight gain." (PMID 29636825, 2018). "Evidence showed that insulin glargine, insulin detemir, and insulin degludec are associated with less overnight hypoglycemia when compared with NPH and relatively less weight gain." (PMID 29508275, 2018).
Hypoglycemia (continued). "The results revealed that their novel tuning method decreased the risk of severe hypoglycemia, especially in patients with low insulin sensitivity." (PMID 29848472, 2018). "Newer, long-acting insulin analogs offer the advantage of flexibility, once-daily dosing, and less risk of hypoglycemia compared with older, cheaper human insulin analogues such as neutral protamine Hagedorn insulin." (PMID 29549574, 2018). "Insulin analogues are associated with a lower risk of hypoglycemia, in particular nocturnal hypoglycemia." (PMID 30116737, 2018). "An example of this was the randomised DCCT, which resolved that patients treated with insulin were more susceptible to severe episodes of hypoglycaemia, as a result of insulins increased susceptibility of neuroglycopenia." (PMID 30417151, 2018). "The incidence of hypoglycemia was higher with canagliflozin treatment in conjunction with insulin therapy, which is also associated with a higher prevalence of falls in patients with T2DM." (PMID 30670968, 2018). "Advanced age is another risk factor for hypoglycemia, and lower insulin doses are usually used in elderly patients." (PMID 29688879, 2018). "The cartridge labels are based on a conservative conversion factor used in a phase 3 study that was intended to reduce the risk of hypoglycemia during the transition from SC insulin to TI." (PMID 29707584, 2018). "The multivariable results confirmed a statistically very significant almost threefold increase in the risk of hypoglycemia among NPH insulin initiators compared to DPP-4 inhibitor initiators (adjusted HR = 2.82; 95% CI: 2.57–3.10)." (PMID 29713649, 2018). "While the use of insulin analogues (e.g. lispro, aspart, glargine and detemir) can be associated with reduced hypoglycaemia and glucose excursions, the safety and efficacy of newer insulin analogues and concentrated insulin preparations need to be clarified." (PMID 29356835, 2018). "Another possible mechanism behind IAS is the presence of a high- capacity, low-affinity paraprotein, capable of causing hypoglycemia associated with high plasma insulin levels and relatively low C-peptide levels." (PMID 30462811, 2018). "Of these agents, GLP-1RA most significantly increased the risk of hypoglycemia relative to all other agents except Met and basal insulin and thus received the worst ranking." (PMID 30148851, 2018). "Dual-hormone closed-loop delivery was chosen to limit the potential hypoglycemia risk associated with overestimation of meal insulin boluses." (PMID 29422651, 2018). "The usual starting point for insulin therapy in T2D is with basal insulin owing to its simplicity and lower risk of hypoglycemia." (PMID 29476414, 2018). "Whenever the heart rate exceeded 125% of its resting value, the algorithm was informed manually which would result in less aggressive insulin delivery and modification of hypoglycemia risk." (PMID 30713524, 2018). "When taking the effect of temperature and exercise into account, it is advisable to reduce the insulin dose and perhaps inject into the slower-absorbing regions under these conditions in order to reduce the risk of iatrogenic hypoglycaemia." (PMID 30116732, 2018). "In humans, mild or moderate hypoglycemic events have been reported only when SGLT-2 inhibitors have been given in conjunction with concurrent insulin or insulin secretagogues, and the risk of hypoglycemia in humans is considered to be low." (PMID 30212530, 2018). "The authors demonstrated that GHD children had an increased susceptibility to hypoglycemia, thus proving to be more insulin-sensitive than GH-sufficient children." (PMID 29942285, 2018). "There is an urgent need for further work, particularly in those at greatest potential risk (i.e. a long duration of insulin treatment and reduced hypoglycaemia awareness)." (PMID 28660491, 2018).
Hypoglycemia (continued). "In both the EDITION 1 trial and the EDITION 2 trial, a lower risk of nocturnal confirmed or severe hypoglycemia was observed with once-daily Glar-300 versus once-daily Glar-100 in participants switching from twice-daily basal insulin." (PMID 29619381, 2018). "Insulin glargine (IGlar) has been proven to pose a lower risk of hypoglycemia than older human insulin formulations." (PMID 29721018, 2018). "Regarding the use of hypoglycaemic drugs, insulin seems to be the most frequent agent associated with severe hypoglycaemia." (PMID 29685177, 2018). "Insulin analogues were developed to mimic the physiological profile of insulin secretion more closely, reduce hypoglycemia risk, and improve bioavailability." (PMID 29460260, 2018). "GIP acts as a physiological blood glucose stabilizer associated with stimulation of insulin and glucagon secretion during hyper- and hypoglycemia, respectively, in healthy subjects and in patients with T2D." (PMID 29941634, 2018). "Insulin-induced hypokalemia and the secretion of adrenaline in response to insulin-induced hypoglycemia have been shown to be a principal cause of these alterations in ECG." (PMID 30105256, 2018). "As a result, patients often have difficulty achieving desired postprandial glucose control, and the long duration of SC insulin activity puts patients at increased risk of delayed postprandial hypoglycemia." (PMID 29707584, 2018). "As insulin glargine provides a more prolonged, consistent duration of action and a lower risk of hypoglycaemia compared to NPH (humane isophane) insulin, glycaemic control improves while having a scarce effect on hypoglycaemia rates." (PMID 28803366, 2018). "A previous study indicated that hypoglycemia is one of the major reasons for emergency hospitalizations for adverse drug events in older Americans, reporting that insulin, instead of tramadol, caused emergency hospitalizations in the United States of America." (PMID 30355965, 2018). "Patients with the disease, who require exogenous insulin treatment, are also at risk of blood glucose fluctuations and hypoglycemia." (PMID 29073149, 2017). "An excellent initial insulin dose estimate is one that provides tight BG control and minimizes the risk of hypoglycemia." (PMID 28044993, 2017). "But, as patients treated with insulin know from experience, too much insulin at any given moment is an acute health hazard as it causes hypoglycemia that interferes with normal brain function." (PMID 28792951, 2017). "Our data suggest that frequent episodes of hypoglycemia were associated with changes in carotid atherosclerosis in insulin-treated patients with T2DM." (PMID 28067320, 2017). "Factors that make these patients susceptible to nocturnal hypoglycemia include decreased autonomic response to hypoglycemia (hypoglycemia-associated autonomic failure) during sleep and decreased insulin-antagonistic hormone response." (PMID 28683068, 2017). "One possible explanation is that there is a higher incidence of fall, due to an increased risk of hypoglycemia associated with hypoglycemia-prone drugs, such as sulfonylureas or insulin." (PMID 29021829, 2017). "While acarbose has a lower risk of hypoglycemia than insulin, caution must be used as it can prevent absorption of carbohydrates resulting in refractory hypoglycemia with oral intake of complex carbohydrates." (PMID 29127952, 2017). "Use of metformin is recommended in guidelines but reported only in a minor part of lean patients while treatment strategies often included insulin, which is associated with increased hypoglycemia." (PMID 28827839, 2017). "Children with T1D are at higher risk of hypoglycemia due to difficulty in insulin dosing, unpredictable activity and ﻿ eating patterns, and limitations in detecting hypoglycemia in this population." (PMID 28115020, 2017).
Hypoglycemia (continued). "Another report by Langer showed that fasting glucose > 105 mg/dL was associated with fetal macrosomia, hypoglycemia in newborn infants, cesarean delivery, and a need for insulin therapy." (PMID 28491872, 2017). "It is therefore important to identify potential factors and associations for hypoglycemia during intensive insulin therapy." (PMID 28271075, 2017). "Patients require continuous intravenous insulin infusion to control glucose level, but intensive insulin therapy (IIT) is often associated with an increased risk of hypoglycaemia." (PMID 28699150, 2017). "Congenital Hyperinsulinism (CHI) is a disease of severe hypoglycaemia caused by excess insulin secretion and associated with adverse neurodevelopment in a third of children." (PMID 28532504, 2017). "Use of the modified Atlanta protocol for continuous insulin therapy minimized the overall risk of severe or prolonged hypoglycemia." (PMID 29075530, 2017). "Insulinoma is the most common functional islet cell tumor of which the most prominent characteristic is the severe status of hypoglycemia caused by improper insulin secretion." (PMID 28293303, 2017). "Parallel to these relatively simple but progressive approaches to mitigate the risk of hypoglycaemia, bolder developments have taken place to link insulin delivery directly to glucose levels." (PMID 28114938, 2017). "Insulin (n = 26), oral antidiabetic drugs (n = 5) or both (n = 1) were the cause of hypoglycemia in two-thirds of cases." (PMID 28534234, 2017). "In our data, increased glycemic variability (range of glucose) was associated with a higher usage of insulin treatment and a higher incidence of hypoglycemia during admission." (PMID 28880933, 2017). "Older patients using both insulin and sulfonylureas were at the highest risk, with an odds ratio of 4.7 (95% CI 3.7–6.1) for hypoglycemia." (PMID 28920012, 2017). "Although modern insulin therapy has led to a reduction in the frequency of severe hypoglycaemic events, tight glycaemic control remains a predisposing factor to hypoglycaemia and its effect is amplified by duration of the disease." (PMID 28094136, 2017). "There was a positive association with the number of daily insulin injections that was statistically significant only for all hypoglycemia (p = 0.000)." (PMID 28913365, 2017). "It is also well established that sulfonylureas (e.g. gliclazide) cause hypoglycemia by stimulating insulin release from pancreatic β-cells." (PMID 28356096, 2017). "Risk of hypoglycemia during or after exercise can be minimized if blood glucose is closely monitored before, during, and after exercise, and individual adjustments in insulin or food intake are made." (PMID 28836234, 2017). "An ideal insulin regimen should mimic physiological insulin release while providing optimal glycemic control with low risk of hypoglycemia, weight gain, and fewer daily injections." (PMID 28167928, 2017). "Through injections, insulin enters the blood circulation directly causing peripheral hyperinsulinemia leading to hypoglycemia, cancer, atherosclerosisand peripheral hypertension." (PMID 30970818, 2017). "The insulin-independent effect of this novel anti-diabetic agent is associated with a low risk of hypoglycemia, which makes it attractive for the management of patients with T2DM." (PMID 29213337, 2017). "This indicates that in a clinical setting an increased initial risk of severe hypoglycaemia should be avoidable with careful blood glucose monitoring and judicious insulin dose-adjustment, particularly at mealtime." (PMID 29029531, 2017). "Other differential diagnosis for patients with hypoglycemia include excessive insulin dosing, pronounced peak of basal insulin, and growth hormone deficiency." (PMID 28748191, 2017). "The increased risk of severe hypoglycaemia is another concern for improving glycaemic control with insulin therapy in T1DM patients." (PMID 29029531, 2017).